USP22 (ubiquitin specific peptidase 22)
Description:
Deubiquitinase that plays a role in several cellular processes including transcriptional regulation, cell cycle progression or innate immunity. As part of the transcription regulatory histone acetylation (HAT) complex SAGA, catalyzes the deubiquitination of both histones H2A and H2B, thereby acting as a transcriptional coactivator. Recruited to specific gene promoters by activators such as MYC, where it is required for transcription. Facilitates cell-cycle progression by stabilizing CCNB1 and antagonizing its proteasome-mediated degradation in a cell cycle-specific manner. Plays multiple roles in immunity and inflammation. Participates in antiviral response by deubiquitinating the importin KPNA2, leading to IRF3 nuclear translocation and subsequent type I interferon production. Acts as a central regulator of type III IFN signaling by negatively regulating STING1 activation and ubiquitination. Inhibits NLRP3 inflammasome activation by promoting NLRP3 degradation through ATG5-dependent autophagy (By similarity). Deubiquitinates CD274 to induce its stabilization and thereby participates in maintenance of immune tolerance to self. Controls necroptotic cell death by regulating RIPK3 phosphorylation and ubiquitination. During bacterial infection, promotes pro-inflammatory response by targeting TRAF6 and removing its 'Lys-48'-linked polyubiquitination (By similarity).
Synonyms: KIAA1063; USP3L
Tractability: PROTAC: UniProt records ubiquitination sites on it; ubiquitination databases record sites on it; its protein half-life has been measured.
Target class: Enzyme; Hydrolase
Gene: Protein-coding gene on chromosome 17 (20,999,596 to 21,043,760, reverse strand). Ensembl gene ENSG00000124422.
Subcellular location: Nucleus; Cytoplasm
Subcellular location (Human Protein Atlas): Nuclear speckles
Pathways (Reactome):
Chromatin organization: HATs acetylate histones
Metabolism of proteins: Ub-specific processing proteases
Gene Ontology:
Molecular function: cysteine-type deubiquitinase activity; enzyme binding; histone H2A deubiquitinase activity; histone H2B deubiquitinase activity; histone H4 acetyltransferase activity; protein binding; transcription coactivator activity; zinc ion binding
Biological process: G2/M transition of mitotic cell cycle; positive regulation of DNA-templated transcription; positive regulation of mitotic cell cycle; positive regulation of type I interferon production; protein deubiquitination; regulation of transcription by RNA polymerase II; embryo development ending in birth or egg hatching; regulation of DNA repair; regulation of RNA splicing; chromatin remodeling
Cellular component: nucleus; SAGA complex; cytoplasm; nucleoplasm; transcription factor TFTC complex
Genetic constraint (gnomAD): Loss-of-function variants: 22 observed, 63.65 expected, observed/expected ratio (o/e) 0.35, 90% interval 0.25 to 0.49. The upper end of that interval is the gene's LOEUF score, 0.49, which puts it in group 2 of 6, group 1 being the genes least tolerant of losing a copy. Missense variants: 428 observed, 667.09 expected, observed/expected ratio (o/e) 0.64, 90% interval 0.59 to 0.69. Synonymous variants: 278 observed, 263.36 expected, observed/expected ratio (o/e) 1.06, 90% interval 0.96 to 1.17.
Homologues: Orthologues: chimpanzee USP22 (99% identical), macaque USP22 (99% identical), guinea pig USP22 (98% identical), rat Usp22 (98% identical), mouse Usp22 (98% identical), rabbit USP22 (97% identical), dog USP22 (95% identical), tropical clawed frog usp22 (90% identical), zebrafish usp22 (90% identical), pig USP22 (87% identical), Drosophila melanogaster not (53% identical). Paralogues in human: USP51 (71% identical), USP27X (67% identical), USP24 (26% identical), USP19 (25% identical), USP15 (25% identical), USP4 (25% identical), USP3 (24% identical), USP33 (24% identical), USP45 (24% identical), USP11 (24% identical), USP2 (23% identical), USP32 (23% identical), and 59 more.
Diseases named in the same sentence as USP22 in open-access papers:
USP22 is named in the same sentence as 96 diseases in open-access papers, as found by Europe PMC text mining. Sharing a sentence is not in itself a finding about the gene and the disease. The quoted sentences say what the papers report.
hepatocellular carcinoma (46 papers, 2015 to 2026). A malignant tumor that arises from hepatocytes. "Analysis of TCGA database reveals that USP22 is highly expressed in hepatocellular carcinoma tissues, which is closely associated with poor patient prognosis." (PMID 40341781, 2025). "To elucidate the mechanisms underlying USP22‐promoted proliferation of hepatocellular carcinoma cells, we speculated that the deubiquitination of substrate proteins catalysed by USP22 probably accounted for the regulatory effects we observed." (PMID 40341781, 2025). "For example, USP22 was reported to promote lipogenesis contributing to hepatocellular carcinoma pathogenesis." (PMID 41541703, 2026). "To further validate that USP22 increases hepatocellular carcinoma cell proliferation by stabilising CDK11B protein, we overexpressed His‐CDK11B in USP22 knockout cells and evaluated cell proliferation." (PMID 40341781, 2025). "Previous studies have shown that USP22 stabilizes PPARγ in hepatocellular carcinoma to regulate lipidome accumulation." (PMID 40448065, 2025). "A subcutaneous tumour model in nude mice was then applied to investigate the in vivo effect of USP22 depletion on hepatocellular carcinoma growth and response to Sorafenib." (PMID 40341781, 2025). "Our data further indicates that USP22 promotes the proliferation of hepatocellular carcinoma cells via deubiquitinating and stabilizing cyclin‐dependent kinase 11B (CDK11B)." (PMID 40341781, 2025). "Taken together, these results indicated that USP22 interacts with CDK11B in hepatocellular carcinoma cells." (PMID 40341781, 2025). "Our study has further reinforced the role of USP22 as a contributor to hepatocellular carcinoma progression and Sorafenib resistance." (PMID 40341781, 2025). "In this study, we found that USP22 is critically involved in the proliferation and drug resistance of hepatocellular carcinoma cells." (PMID 40341781, 2025). "Meanwhile, immunohistochemical staining data sourced from The Human Protein Atlas database corroborated a marked increase in USP22 protein expression in hepatocellular carcinoma tissues than normal tissues." (PMID 40341781, 2025). "Collectively, these findings demonstrated that USP22 promotes the proliferation of hepatocellular carcinoma cells in vitro." (PMID 40341781, 2025). "The small molecule inhibitors targeting USP22 can be explored in future to function alone or synergistically with Sorafenib to treat hepatocellular carcinoma." (PMID 40341781, 2025). "These series data suggested a potential involvement of USP22 in the progression of hepatocellular carcinoma." (PMID 40341781, 2025). "Taken together, this study demonstrates that USP22 promotes hepatocellular carcinoma growth and inhibits Sorafenib‐induced ferroptosis by deubiquitinating non‐histone substrate CDK11B and histone H2B, respectively." (PMID 40341781, 2025). "In summary, our study demonstrated that USP22 promotes the growth of hepatocellular carcinoma and resistance to Sorafenib‐induced ferroptosis by removing ubiquitin moieties from non‐histone protein CDK11B and histone H2B." (PMID 40341781, 2025). "In hepatocellular carcinoma, ubiquitin-specific protease 22 (USP22) has been shown to stabilize ZEB1 and thereby upregulate ZEB1-mediated VEGF-A transcription." (PMID 41226394, 2025). "We have demonstrated that USP22 depletion inhibits hepatocellular carcinoma cell proliferation and promotes the sensitivity of hepatocellular carcinoma cells to Sorafenib‐induced ferroptosis by in vitro assays." (PMID 40341781, 2025). "Our findings suggest USP22 as a promising prognostic biomarker and therapeutic target for hepatocellular carcinoma patients, particularly those with Sorafenib resistance." (PMID 40341781, 2025).
hepatocellular carcinoma (continued). "USP22 promotes the proliferation of hepatocellular carcinoma cells via deubiquitinating and stabilising cyclin‐dependent kinase CDK11B, and it inhibits Sorafenib‐induced ferroptosis by decreasing H2BK120ub occupancy at TFRC TSS downstream region." (PMID 40341781, 2025). "In this study, we demonstrated USP22 as a novel driver of Sorafenib resistance in hepatocellular carcinoma, presenting a new potential therapeutic target for Sorafenib‐resistant hepatocellular carcinoma." (PMID 40341781, 2025). "Altogether, these results provided evidence that USP22 promotes the proliferation of hepatocellular carcinoma cells by stabilising CKD11B and increases Sorafenib resistance through reducing H2BK120ub level and TFRC transcription in vivo." (PMID 40341781, 2025). "To establish the relationship between the promotion of cell proliferation and the stabilisation of CDK11B protein caused by USP22 overexpression, we intended to first examine the effects of CDK11B knockdown on hepatocellular carcinoma cell proliferation." (PMID 40341781, 2025). "In this study, we demonstrate that USP22 promotes the proliferation of hepatocellular carcinoma cells by stabilising cyclin‐dependent kinase 11B (CDK11B)." (PMID 40341781, 2025). "To investigate the effect of USP22 overexpression on hepatocellular carcinoma cell proliferation, we infected HepG2 and Hep3B cells with lentiviruses and established cell lines stably overexpressing Flag‐USP22 or not." (PMID 40341781, 2025). "USP22 promotes the proliferation of hepatocellular carcinoma cells by stabilising CDK11B and enhances resistance to Sorafenib by inhibiting ferroptosis through the USP22/H2BK120ub/TFRC axis." (PMID 40341781, 2025). "For instance, resistance in hepatocellular carcinoma involves the p-MYH9/USP22 axis stabilizing HIF-1alpha, promoting stemness and lenvatinib resistance, while in pancreatic cancer, targeting MXD1 overcomes trametinib resistance." (PMID 40696490, 2025). "A series of cellular experiments related to cell proliferation and ferroptosis, and mouse tumor‐bearing experiments were performed to investigate the role of USP22 in hepatocellular carcinoma cell growth and Sorafenib resistance." (PMID 40341781, 2025). "Our analysis unveiled a significant upregulation of USP22 mRNA levels in hepatocellular carcinoma tissues compared to adjacent normal tissues." (PMID 40341781, 2025). "To investigate the role of USP22 in hepatocellular carcinoma development, we initially analysed USP22 expression levels in hepatocellular carcinoma tissues and normal tissues utilising the The Cancer Genome Atlas (TCGA) database." (PMID 40341781, 2025). "Ubiquitin‐specific protease 22 (USP22) expression level and its prognostic significance in hepatocellular carcinoma were analyzed using The Cancer Genome Atlas (TCGA) database." (PMID 40341781, 2025). "The research team achieved high tumor suppression and increased sensitivity to sorafenib in mice with hepatocellular carcinoma by targeting USP22 with a lipid-polymeric complex." (PMID 39048965, 2024). "In hepatocellular carcinoma, the deubiquitinating enzyme USP22 directly interacts with the C-terminus of PD-L1, catalyzing its deubiquitination and stabilization." (PMID 38762484, 2024). "This further indicates that USP22 is a highly promising therapeutic target for hepatocellular carcinoma." (PMID 39048965, 2024). "For example, USP22 was reported to promote vascularization in the mouse placenta and aberrant angiogenesis in hepatocellular carcinoma and non-small cell lung cancer." (PMID 38347585, 2024). "USP22 is not only expressed at elevated levels in hepatocellular carcinoma but also closely related to the malignant behavior of tumors." (PMID 35935969, 2022).
hepatocellular carcinoma (continued). "Here, the authors show that PPARgamma is stabilized by USP22-mediated deubiquitination leading to lipid accumulation and promoting hepatocellular carcinoma." (PMID 35449157, 2022). "USP22 can promote multidrug resistance (MDR) in hepatocellular carcinoma cells by activating the SIRT1/AKT/MRP1 pathway, which contributes to tumorigenesis and progression of hepatocellular carcinoma." (PMID 36176401, 2022). "Hepatocellular carcinoma is the tumor that better fits in the exploration of tumor inhibition mediated by USP22–PD-L1, because the expression of USP22 in this tumor is higher than its expression in other cancer types." (PMID 32850399, 2020). "USP22 is a biomarker for advanced malignancy in numerous tumor types, including non-small cell lung cancer, gastric carcinoma and hepatocellular cancer." (PMID 28427243, 2017). "The expression frequency and expression levels of USP22 were significantly higher in hepatocellular carcinoma (HCC) than in normal liver tissues." (PMID 25909224, 2015). "Additionally, USP22 acts as a novel inducer of Sorafenib resistance and suppresses Sorafenib‐triggered ferroptosis in hepatocellular carcinoma cells." (PMID 40341781, 2025). "Our findings underscore the crucial role of USP22 in hepatocellular carcinoma development and Sorafenib resistance, suggesting that USP22 may serve as a promising therapeutic target for hepatocellular carcinoma." (PMID 40341781, 2025). "Additionally, colony formation ability of hepatocellular carcinoma cells was suppressed subsequent to USP22 knockout/knockdown." (PMID 40341781, 2025). "After we had confirmed that USP22 promotes the growth of hepatocellular carcinoma, we further focused on exploring whether USP22 regulates Sorafenib resistance in hepatocellular carcinoma." (PMID 40341781, 2025). "Finally, animal experiments confirm the role of USP22 in promoting hepatocellular carcinoma cell growth and Sorafenib resistance in vivo." (PMID 40341781, 2025). "The results manifested that USP22 interacts with CDK11B in hepatocellular carcinoma cells." (PMID 40341781, 2025). "USP22 upregulates the expression of ACC and ACLY by promoting the K48-linked ubiquitination of PPARγ, ultimately fostering lipid accumulation and tumorigenesis in hepatocellular carcinoma cells." (PMID 39048965, 2024). "Research shows that inhibition of USP22 can increase the sensitivity of hepatoma cells to 5-FU." (PMID 35935969, 2022). "Ubiquitin-specific protease 22 (USP22) stabilizes PPARγ due to deubiquitination, which increases acetyl-CoA carboxylase (ACC) and ATP citrate lyase (ACLY) expression and induces de novo lipogenesis as a risk factor for hepatocellular carcinoma (HCC)." (PMID 35954274, 2022). "Similarly, USP22 was also shown to promote hepatocellular cancer cell chemotherapy resistance, nasopharyngeal carcinoma progression, and gastric cancer tumorigenic properties by stimulating the PI3K/AKT- and the MAPK-signaling." (PMID 34007022, 2021). "In addition, USP22 has been reported to regulate ZEB1 ubiquitination to promote the transcription of downstream genes in hepatocellular carcinoma, and we considered whether a similar phenomenon could be observed in OC." (PMID 39530604, 2024). "Ubiquitin‐specific protease 22 (USP22) has been identified as a potential marker for cancer stem cells in hepatocellular carcinoma (HCC)." (PMID 38045832, 2023). "It is worth noting that a recent study showed that USP22 can regulate the ubiquitination of PD-L1 in hepatocellular carcinoma (HCC) cells." (PMID 34350172, 2021). "A galactose‐decorated lipopolyplex (Gal‐SLP) is developed as a hepatocellular carcinoma (HCC)‐targeting self‐activated cascade‐responsive nanoplatform to co‐deliver sorafenib and USP22 shRNA (shUSP22) for synergetic HCC therapy." (PMID 33717848, 2021).